IGLV3-27 (immunoglobulin lambda variable 3-27)
Description:
V region of the variable domain of immunoglobulin light chains that participates in the antigen recognition. Immunoglobulins, also known as antibodies, are membrane-bound or secreted glycoproteins produced by B lymphocytes. In the recognition phase of humoral immunity, the membrane-bound immunoglobulins serve as receptors which, upon binding of a specific antigen, trigger the clonal expansion and differentiation of B lymphocytes into immunoglobulins-secreting plasma cells. Secreted immunoglobulins mediate the effector phase of humoral immunity, which results in the elimination of bound antigens. The antigen binding site is formed by the variable domain of one heavy chain, together with that of its associated light chain. Thus, each immunoglobulin has two antigen binding sites with remarkable affinity for a particular antigen. The variable domains are assembled by a process called V-(D)-J rearrangement and can then be subjected to somatic hypermutations which, after exposure to antigen and selection, allow affinity maturation for a particular antigen.
Synonyms: IGLV327; V2-19
Tractability: Antibody: its Gene Ontology location is reachable by antibodies, with high confidence; UniProt places it where antibodies can reach, with medium confidence; UniProt predicts a signal peptide or a membrane-spanning region.
Gene: Immunoglobulin variable (V) gene on chromosome 22 (22,668,288 to 22,668,806, forward strand). Ensembl gene ENSG00000211658.
Subcellular location: Secreted; Cell membrane
Pathways (Reactome):
Immune System: Antigen activates B Cell Receptor (BCR) leading to generation of second messengers; CD22 mediated BCR regulation; Classical antibody-mediated complement activation; FCERI mediated Ca+2 mobilization; FCERI mediated MAPK activation; FCERI mediated NF-kB activation; FCGR activation; Fc epsilon receptor (FCERI) signaling; Immunoregulatory interactions between a Lymphoid and a non-Lymphoid cell; Initial triggering of complement; Regulation of Complement cascade; Regulation of actin dynamics for phagocytic cup formation; Role of LAT2/NTAL/LAB on calcium mobilization; Role of phospholipids in phagocytosis
Disease: FCGR3A-mediated IL10 synthesis; FCGR3A-mediated phagocytosis; Potential therapeutics for SARS
Hemostasis: Cell surface interactions at the vascular wall
Vesicle-mediated transport: Scavenging of heme from plasma
Gene Ontology:
Molecular function: antigen binding
Biological process: immune response
Cellular component: extracellular region; immunoglobulin complex; plasma membrane
Homologues: Orthologues: macaque IGLV3-27 (66% identical), tropical clawed frog igl (53% identical). Paralogues in human: IGLV3-25 (86% identical), IGLV3-10 (83% identical), IGLV3-16 (82% identical), IGLV3-22 (75% identical), IGLV3-1 (74% identical), IGLV3-9 (69% identical), IGLV3-19 (67% identical), IGLV3-21 (66% identical), IGLV3-12 (64% identical), IGLV3-32 (64% identical), IGLV6-57 (57% identical), IGLV2-11 (56% identical), and 81 more.